EGF (epidermal growth factor)
Diseases named in the same sentence as EGF in open-access papers (continued):
Sharing a sentence is not in itself a finding about the gene and the disease.
tumor (continued). "The MNT DTox-HMP-NLS-EGF with human EGF as a ligand module was designed as a platform for delivering a cytotoxic agent to the nucleus of tumor cells overexpressing EGFR." (PMID 30510514, 2018). "In contrast, daily EGF administration beginning ~2 months after tumor initiation (“late”) increased tumor size." (PMID 29904166, 2018). "Neutrophils produce and secrete tumor-promoting growth factors, such as epidermal growth factor, vascular endothelial growth factor, interleukin (IL)-6 and IL-8, that can promote tumor cell activation and facilitate tumor development, invasion and metastasis." (PMID 29618336, 2018). "TAMs suppress the anti-tumor immune response via the secretion of anti-inflammatory cytokines, including IL-10, and supply the tumor with growth factors such as EGF and VEGF, which promote primary tumor growth and angiogenesis." (PMID 29805773, 2018). "M2 TAMs support tumor progression by directly stimulating the growth of cancer cells through the production of growth factors, including EGF, TNFα, IL-6." (PMID 30356656, 2018). "Initial studies on brain tumor cancer stem cells were based on the growth of brain tumor cells in serum free media containing EGF and bFGF, allowing the formation and growth of cluster of precursor tumor cells, called neurospheres." (PMID 30279357, 2018). "In particular, EGF signaling via the EGFR can stimulate tumor cell proliferation and promote bone metastasis in PC." (PMID 29890952, 2018). "The expression of PD-L1 on tumor cells is induced by EMT, IFN-γ, tumor necrosis factor-α (TNF-α), and EGF in the inflammatory tumor microenvironment." (PMID 30126206, 2018). "Addition of hydrocortisone + EGF 20 ng/ml (5%), folic acid 6 mg/L (4%) and hydrocortisone (3%) improved proliferation of tumor cells in the tissue fragments." (PMID 29861851, 2018). "Killing tumor cells by optical methods was also shown when gold nanoparticles were functionalized using antibodies against EGF- or TF- receptorsel." (PMID 30297847, 2018). "A further example illustrating the mechanisms of cell death evasion present in tumour cells was obtained investigating the ectopic activation of the Epidermal Growth Factor (EGF) signalling pathway." (PMID 29854765, 2018). "Known roles for stromal ADAM12 are manifold: the well characterized function of ADAM12 as a sheddase of growth factor receptor ligands such as EGF can provide a nurturing environment for tumor cells." (PMID 30442938, 2018). "Spatio-temporal analyses in vitro revealed that perturbation of signaling pathways relevant for the initiation and maintenance of a migration front phenotype (e.g. the EGF/EGFR pathway) only partly reduced tumor cell motility." (PMID 28649432, 2017). "Our study thus provides unprecedented insights into brain tissue infiltration of SHH and G3 MB cells and reveals the cellular basis of the tumour progressing functions of EGF in SHH MB." (PMID 28706234, 2017). "Our model suggests that the EGF/EGFR/arginase II pathway represents a potential therapeutic target to prevent hypoxia induced proliferation in tumor cells." (PMID 28330951, 2017). "Our previous studies suggest that exogenous administration of EGF inhibits growth and induces death in tumor cells." (PMID 27935858, 2017). "Tumour cells under EGF treatment also occupied a markedly larger slice area than in untreated slices." (PMID 28706234, 2017). "Amplification of EGFR was verified in single cells from tumor imprint specimen and in cells after 6 passages of adherent culture in EGF supplemented media." (PMID 28148893, 2017). "Taken together, this report demonstrates that anterograde lysosome trafficking is necessary for EGF-mediated tumor invasion and begins to characterize the molecular mechanisms required for EGF-stimulated lysosome trafficking." (PMID 28978320, 2017).
tumor (continued). "Vascular endothelial growth factor (VEGF) is the major growth factor in tumor angiogenesis, and basic fibroblast growth factor (bFGF) and epidermal growth factor (EGF) interact with VEGF during this process." (PMID 28468300, 2017). "Collectively, these results suggest PKCε-mediated MIIP-S303 phosphorylation facilitates the interaction between MIIP and RelA, which is required for EGF-induced tumor cell invasion." (PMID 29038521, 2017). "Considering growth factors, HCCLM3 cells from metastatic regions expressed significantly higher levels of epidermal growth factor (EGF) than HCCLM3 cells extracted from the primary tumor site." (PMID 28205428, 2017). "As we noted a significant growth inhibition of the combination either in basal condition or in EGF-treated cells, we conclude that HT enhances efficacy of cetuximab on tumor cells." (PMID 29137335, 2017). "Bound and internalization of EGF-IGF-LDP-AE to NSCLC cells was the prerequisite to exert its tumor cell killing effect." (PMID 28460483, 2017). "In in vivo studies accumulation of NP was observed in MDA-MB-468 xenografts and tumour uptake was enhanced by the coadministration of 15 μg of the unlabelled targeting ligand, EGF, to block hepatic EGFR." (PMID 29071190, 2017). "Based on quantification of the experiments with EGF-Rh, at least ~50% of cells in the tumor are accessible to the circulating ligands." (PMID 29268862, 2017). "An anti-tumor treatment cycle of 4 mg·kg−1 EGF(scFv)–MAP intravenously administered to mice at 11 days after tumor challenge resulted in a significant reduction in tumor growth when compared to the control group that received phosphate-buffered saline (PBS)." (PMID 28653985, 2017). "Together, these experiments confirmed EGF as a strong promoter of cell proliferation and migration in MB and demonstrated its potential to drive brain tissue infiltration of the tumour cells." (PMID 28706234, 2017). "A paracrine interaction between CSF-1-secreting tumor cells and epidermal growth factor (EGF)-secreting TAMs stimulates relay chemotaxis through direct cell-cell contact, leading to invasion of both cell types together towards blood vessels." (PMID 28629162, 2017). "As our analysis predicts low EGFR ligand concentrations in tumor xenografts in vivo, we examined which signaling cascades are activated by the same EGF concentrations in cultured cells in vitro." (PMID 29268862, 2017). "We next determined the critical role of glycolysis in EGF-facilitated regional cervical lymph node (LN) metastasis in an orthotopic tumor model of human OSCC in the tongue of nude mice." (PMID 27926487, 2017). "Various mediators are involved in this process, including transforming growth‐factor beta (TGFβ), and molecules produced by supportive tumor stroma, namely epidermal growth factor (EGF) and colony‐stimulating factor 1 (CSF‐1)." (PMID 28017284, 2017). "In contrast to classical growth factors such as EGF which stimulate proliferation of wild-type organoids, we found that PPARD activation is only sufficient to drive growth with concurrent tumor suppressor loss." (PMID 29143738, 2017). "Activation of EGFR on tumour cells by EGF in turn upregulated VEGF/VEGFR signalling in surrounding tumour cells to support tumour cell proliferation and migration." (PMID 29065107, 2017). "Outcomes from our in vitro and in vivo studies support this prediction as they found that BB-Cl-Amidine suppressed EGF-induced tumor cell migration and invasion." (PMID 28549415, 2017). "To confirm our findings in vivo, we evaluated the effect of EGF on tumor growth in an A549 cell xenograft model of solid lung carcinoma." (PMID 27935858, 2017). "So far, studies have shown that TAMs support tumor growth rather indirectly by generating an immunosuppressive milieu and producing pro-tumorigenic cytokines such as the epidermal growth factor (EGF)." (PMID 28750018, 2017).
tumor (continued). "EGF is used as a metastatic inducer and induces tumor cell invasion and metastasis and the downregulation of Focal Adhesion Kinase26." (PMID 28811522, 2017). "At the same time, tumor cells secrete colony-stimulating factor-1 (CSF-1) which in turn promote the expression of EGF by macrophages." (PMID 28970798, 2017). "Four preclinical studies evaluated anti-EGFR antibodies or EGF labeled with a fluorescent compound to discriminate tumor cells from adjacent brain tissue." (PMID 27878374, 2017). "EGFR and HER2 are the members of the HER family, whose EGF signaling pathway is known to play a crucial role in tumor initiation, progression and metastasis." (PMID 28187748, 2017). "In our human cell tumor cultures, EGF stimulation induced a significant increase in HO-1, both at mRNA and protein expression levels, and a significant reduction in 5-ALA fluorescence." (PMID 28500562, 2017). "Tumour uptake of 111In-EGF-Au-PEG6000 in vivo was shown to be enhanced by coadministration of unlabelled targeting ligand, and this was accompanied by a reduction in liver uptake." (PMID 29071190, 2017). "Using the MMTV-PyMT model, it was found that CD4+ T helper cells can induce alternative activation of TAMs and secretion of EGF, to directly promote tumor invasion and egress from the primary tumor as a result of IL4 activation." (PMID 28883015, 2017). "EGF also stimulates the secretion of CSF-1 by tumor cells, thereby forming a positive feedback loop between tumor cells and macrophages." (PMID 28955335, 2017). "In preclinical studies involving radiolabelled EGF, such strategies have also been exploited to increase tumour uptake while reducing liver uptake 29-31." (PMID 29071190, 2017). "The present study defines a role for anterograde lysosome trafficking as a necessary event for EGF-mediated protease secretion and tumor cell invasion in DU145 cancer cells." (PMID 28978320, 2017). "In the last decade, it was well described that macrophages secrete matrix-remodeling proteins, cytokines and chemokines (e.g. MMP, TNF-α, EGF, TGFβ) that can induce the migration and proliferation of tumor cells, 37–39." (PMID 28790339, 2017). "EGF is well-known for its ability to enhance the invasion of tumor cells, while CSF1/2 are able to recruit stromal cells, such as macrophages, to the tumor cells." (PMID 28008153, 2017). "During metastasis of GBM, the signals of epithelial growth factor (EGF) are amplified by the EGF receptor (EGFR) to promote tumor growth and survival." (PMID 29029486, 2017). "The silencing of HIF-1β expression suppressed tumor cell growth and inhibited the expression of tumor growth-related factors, such as vascular endothelial growth factor, epidermal growth factor, and hepatocyte growth factor." (PMID 28053598, 2017). "Tumor-associated overexpressions of TGF-β, TGF-α, EGF, VEGF and TNF-α promote GBM cell survival and proliferation." (PMID 28883992, 2017). "The results confirmed that these Nbs inhibited perfectly EGF-induced signaling and EGF-induced cell proliferation in vitro and prevented the tumor outgrowth in animal models." (PMID 29276515, 2017). "Consistently, the quantification of the volume of the LA-EGFP signal in the image stacks acquired from EGF-treated slices displayed a significant increase in the tumour volume compared to the untreated control." (PMID 28706234, 2017). "Compound 65, later isolated from a Fijian Leucetta, was evaluated as selective inhibitor of the epidermal growth factor (EGF) and inhibited human tumour xenografts in mice." (PMID 29215579, 2017). "Epidermal growth factor released by these macrophages increased tumor cell migration and metastasis." (PMID 28670313, 2017). "Indirect co-cultures of both astrocytes as well as microglia also induced tumor cell migration comparable to EGF-treated media." (PMID 28008153, 2017).
tumor (continued). "EGF, one of the most abundant growth factors found in the tumor microenvironment, can be produced by cancer cells per se and non-cancerous cells such as mesenchymal stromal cells, endothelial cells, and macrophages." (PMID 27926487, 2017). "Taken together, these findings implicate PAD2 in EGF-mediated mammary gland development and tumor cell migration." (PMID 28549415, 2017). "Leukocytes are important in acute inflammation to eliminate pathogens but, in a chronically activated state, they can promote tumor progression by secretion of TGFβ, epidermal-growth-factor, and proteolytic enzymes." (PMID 29085358, 2017). "This study demonstrates for the first time that EGF can stimulate lysosome trafficking to the cell periphery and that EGF-induced lysosome trafficking is necessary for protease secretion and tumor cell invasion medicated in part through p38 MAPK activation." (PMID 28978320, 2017). "Tumor invasion through a basement membrane is one of the earliest steps in metastasis, and growth factors, such as Epidermal Growth Factor (EGF) and Hepatocyte Growth Factor (HGF), stimulate this process in a majority of solid tumors." (PMID 28978320, 2017). "In order to study the role of EGF-CFC family molecules in NB tumor sphere formation, the expression levels of CFC1, TDGF1, ACVR2A, ACVR2B, and ACVR1B were measured using a microarray." (PMID 28620148, 2017). "Both glial cells can highly activate MDA-MB-231 BR tumor cell migration in a similar manner as EGF stimulation." (PMID 28008153, 2017). "In many tumors EGF is produced either by the tumor cells themselves or is available from surrounding stromal cells, leading to constitutive EGFR activation." (PMID 28038470, 2017). "It is also known that EGF promotes tumor angiogenesis, cell motility, and invasion, and that EGFR stimulates cell migration through receptor phosphorylation and subsequent activation of downstream signaling pathways." (PMID 28629170, 2017). "CSF-1 also stimulates macrophages to release EGF, which promotes tumor cell proliferation and migration." (PMID 28955335, 2017). "MiR-10b overexpression accelerated PCC proliferation and tumor growth; miR-10b enhanced the stimulatory effects of EGF and TGF-β on cell migration and EMT, decreasing the expression of RAP2A, EPHB2, KLF4 and NF1." (PMID 29254283, 2017). "Knockdown of MCT1 expression caused decreased hepatocyte growth factor (HGF)-induced as well as epidermal growth factor (EGF)-induced tumor cell scattering and wound healing." (PMID 27127175, 2016). "Several signals from the tumor microenvironment have been shown to trigger EMT processes via specific pathways involving epidermal growth factor (EGF), transforming growth factor (TGF)-β, hepatocyte growth factor (HGF), Notch and Wnt/β-catenin signaling." (PMID 27015552, 2016). "Similar to what we observed as regards cathepsin B secretion, HGF and EGF-induced tumor cell invasion and motility were also significantly reduced following treatment with niclosamide." (PMID 26784896, 2016). "Isolated primary GC cells from human tumor tissues or GC cell lines were cultured in a serum-free medium with recombinant epidermal growth factor (EGF) and basic fibroblast growth factor (bFGF)." (PMID 26769843, 2016). "The expression of t-PA is also regulated by a variety of effectors including cytokines tumor necrosis factor, interleukin, epidermal growth factor, and retinoid tumor promoters." (PMID 27635131, 2016). "EGF was found to heavily influence cell proliferation and invasion distance to which by day 4, there were stark differences in tumor area coverage between the two studied conditions." (PMID 27678304, 2016). "Our previous studies and those of others have shown promising evidences about fusing CD with targeting molecules (e.g. EGF) for tumor treatment." (PMID 26801910, 2016).
tumor (continued). "We compared gene lists ascribed to these pathways in the tumor transcriptome with those for EGF or ERBB signaling and Wnt β-catenin signaling, which were also enriched in the tumor transcriptome." (PMID 27910913, 2016). "When cells harvested from tumor specimens are grown in a serum‐free media supplemented with epidermal growth factor (EGF) and basic fibroblast growth factor (bFGF), CSCs as well as normal stem cells form spheres or grow into colonies." (PMID 26773710, 2016). "Particularly, HGF signaling through its cognate receptor, c-Met, can induce cancer cells to undergo an EMT typified by loss of cell-cell adhesions and increased cell motility, leading to tumor cell invasion and metastasis; the same is true for EGF signaling." (PMID 27127175, 2016). "By replacing the EGF moiety with targeting moieties for different receptors, this approach can be applied to additional tumor types." (PMID 27598772, 2016). "Internalization of EGFR/ligand (EGF or anti-EGFR antibodies) is a physiological mechanism affecting the tumor cell response to growth and inhibition stimuli." (PMID 26575422, 2016). "Although EMT is not completely dependent on EMT regulators such as Snail, Twist, and Zeb-1/-2, analysis of upstream signaling (i.e., TGF-β, EGF, Wnt) is necessary to understand tumor EMT more comprehensively." (PMID 26828526, 2016). "Estrogens are functional in normal lung and tumor cell lines and can directly stimulate the transcription of estrogen-responsive genes in the nucleus of lung cells, thereby transactivating the epidermal growth factor pathway." (PMID 27713172, 2016). "In the vascular system, they influence the migration of tumour cells, the liberation of cytokines and growth factors linked to the cellular membrane, such as the transforming growth factor alpha TGF-α and the epidermal growth factor EGF." (PMID 26913068, 2016). "For example, Cetuximab that targets the epidermal growth factor conjugated with 90Y was effective in controlling tumor growth." (PMID 27270318, 2016). "VEGF-induced lymphangiogenesis and EGF-induced angiogenesis can enhance the development of lymphatic and vessels within and close to tumors and thereby promote the spread of tumor cells to regional lymph nodes." (PMID 26443540, 2016). "It is well known that a positive feedback loop exists between TAMs and tumor cells, involving epidermal growth factor (EGF) and CSF-1." (PMID 26980947, 2016). "Previous studies showed that in addition of factors like VEGFA and bFGF, which promote tumor angiogenesis, myelomonocytic cells also produce EGF, HGF, MMP-9 and other cytokines that directly enhance the tumor cell survival, growth and invasion." (PMID 27391260, 2016). "Using 3D time-lapse imaging, we tracked individual cells, which was further analyzed in NIS Elements AR Microscope Imaging Software by Nikon, to investigate the effects of EGF on 3D tumor cell migration within the initial 24 h of adding EGF." (PMID 27678304, 2016). "Some of their substrates are growth factors or cytokines such as TNF-α and EGF, relevant for development and tumor cell expansion." (PMID 27834810, 2016). "Tumor-associated macrophages (TAMs) gather around blood vessels and create gradients of EGF within the tumor environment that attract tumor cells towards blood vessels and promote intravasation." (PMID 27270649, 2016). "The promotion-sensitive mouse epidermal cells JB6 Cl41 are known to respond irreversibly to tumor promoters such as epidermal growth factor (EGF) with induction of anchorage-independent growth in soft agar." (PMID 26936995, 2016). "MKN-45 single cells and tumor tissue fragments in defined serum free medium (SFM) supplemented with EGF, bFGF and B27 formed bodies that resembled spheres which were loosely attached cells that had a grape-like shape." (PMID 26862521, 2016).